CDKN2A (cyclin dependent kinase inhibitor 2A)
Diseases named in the same sentence as CDKN2A in open-access papers (continued):
Sharing a sentence is not in itself a finding about the gene and the disease.
skin cancer (34 papers, 2004 to 2025). "Various risk factors in SPCs associated with breast and skin cancers include age, gender, socio-cultural factors, radiotherapy, chemotherapy, and mutations in BRCAs, CDKN2A, VDK4, and BAP1." (PMID 39917137, 2025). "Studies have shown that genetic counseling for individuals with CDKN2A pathogenic variants can significantly influence their adherence to skin cancer prevention, including routine skin examinations and UV protection measures." (PMID 41373161, 2025). "Cdkn2ab knockout mice, deficient for three reading frames (p15INK4b, p19ARF, and p16INK4a), developed a wider spectrum of tumors than Cdkn2a -/- mice, with a higher proportion of skin carcinomas." (PMID 33445626, 2021). "To date, there is a lack of information about the mechanisms underlying the increased skin cancer risk in carriers of CDKN2A mutations in association with MC1R variants." (PMID 24742402, 2014). "The aim of the study was to determine the constitutional effect of germline CDKN2A mutations or MC1R variants in skin cancer, in order to identify early critical molecular targets implicated in the disease." (PMID 24742402, 2014). "Mutations in the Hras, Pten, Pi3k, Mdm2, Tp63, Esr, Pgr, and Her2 genes, loss of Cdkn2a, Igf, and Akt, as well as MYC phosphorylation have been identified in DMBA-induced breast, blood, and skin tumor models." (PMID 41426972, 2025). "In the PCAWG skin cancer cohort, we found that a monoallelic predictive model of CDKN2A-d achieved relatively high accuracy (PR-AUC-E = 0.28; AUROC = 0.82)." (PMID 36883553, 2023). "Skin tumours develop in a small fraction (10%) of Cdkn2a knockout mice hemizygous for Cdkn2b, however, with a much longer latency than full Cdkn2ab knockout mice." (PMID 30926782, 2019). "Nevertheless, cfDNA can provide information on copy number alterations by reflecting changes in CCNB2 and CDKN2A/B in patients with lung, brain, breast, and skin cancer." (PMID 29728089, 2018). "Overall, skin cancer had the highest somatic mutation frequencies for genes within cancer susceptibility regions, with SORCS3, CDKN2A, and TRIOBP all having mutations in over 10 % of samples." (PMID 26374197, 2015). "We studied the impact of the CDKN2A germinal mutation p.G101W and MC1R variants on gene expression and transcription profiles associated with skin cancer." (PMID 24742402, 2014). "Deletions on chromosomes 7 and 9 were observed and mapped to regions containing the tumor suppressor genes CDKN2A (which encodes p16Ink4A) and TES that are often inactivated in some lung, prostate and skin tumors." (PMID 23880854, 2013). "Firstly, when we compared the genetic correlation, and the MTAG results before and after excluding genomic regions (HLA, ASIP, IRF4, MC1R, SLC45A2 and CDKN2A) with very large effect sizes for skin cancers and pigmentation traits, and there was a high concordance." (PMID 36496446, 2022). "Additionally, the optimized preparation was assessed for its safety, DNA damage and fragmentation, and the expression alteration of the cyclin-dependent kinase inhibitor 2A (CDKN2A) gene related to skin cancer progression." (PMID 36678651, 2022). "Indeed, qPCR assays show that WNT signalling enhanced CyclinD transcription in both Cdkn2a KO and Cdkn2ab KO MEFs and transcription of both Cdk6 and CyclinD in the skin carcinoma cell lines." (PMID 30926782, 2019). "Likewise, copy-number alterations, such as loss of CDKN2A, were detected in skin tumours but not matched bone marrow samples." (PMID 37286599, 2023). "The first generations of Cdkn2ab knockout mice on a mixed 129P2;FVB/N background frequently developed skin tumours and various soft tissue sarcomas, tumour types not normally seen in Cdkn2a−/− mice." (PMID 30926782, 2019).
skin cancer (continued). "Moreover, the level of CDKN2A gene expression was significantly (p ≤ 0.01, ANOVA/Tukey) decreased in skin cancer cell lines relative to normal skin cell lines, indicating that TES are a good carrier for topical delivery of CXB to the cancer cells, suppressing their progression." (PMID 36678651, 2022). "Moreover, the level of expression of the CDKN2A gene was significantly (p ≤ 0.01, ANOVA/Tukey) decreased in skin tumor cell lines compared with normal skin cell lines, indicating that TES are the suitable carrier for topical delivery of CXB to the cancer cells suppressing their progression." (PMID 36678651, 2022). "No promoter hypermethylation of FHIT or CDKN2A was identified in MCC, BCC, AK, or other skin tumors (data not shown)." (PMID 22768181, 2012).
cervical intraepithelial neoplasia (33 papers, 2004 to 2025). "The methylation of CDKN2A promoter may occur between low-grade and high-grade cervical dysplasia and is common in invasive carcinoma which express the E7 oncoprotein." (PMID 32025240, 2020). "In cervical intraepithelial neoplasia, p16INK4a (CDKN2A, cyclin-dependent kinase inhibitor 2A) was shown to indicate malignancy and progression into carcinoma." (PMID 19516893, 2008).
pancreatic adenocarcinoma (33 papers, 2009 to 2026). "In preclinical studies involving pancreatic adenocarcinoma cell cultures with a CDKN2A gene mutation, CDK4/6 inhibitors demonstrated antiproliferative activity against these cancer cells." (PMID 38137564, 2023). "CDKN2A coding region germline variants are associated with pancreatic adenocarcinoma (PC) susceptibility." (PMID 29216274, 2017). "Additionally, similar results were obtained from the profiling of mutations in SMAD4 and CDKN2A, which are frequently observed in patients with regular pancreatic adenocarcinoma." (PMID 39651731, 2024). "Bioinformatics analysis of TCGA’s pancreatic adenocarcinoma data underscored the importance of CDKN2A inactivation in PDAC." (PMID 38666907, 2024). "The rates of digestive adenocarcinoma without APC, KRAS, and CDKN2A alterations in patients with biliary tract, gastric, colorectal, and pancreatic adenocarcinomas were 54.8%, 21.0%, 18.5%, and 5.6%, respectively." (PMID 38672586, 2024).
neurofibroma (32 papers, 2005 to 2025). An intraneural or extraneural neoplasm arising from nerve tissues and neural sheaths. "In concordance with established tumorigenesis pathways, our dataset showed significant loss of CDKN2A in MPNSTs relative to neurofibromas (in gray)." (PMID 40802750, 2025). "In fact, loss of CDKN2A has been used as a marker to suggest that atypical neurofibromas are precursor lesions of MPNSTs." (PMID 37837931, 2023). "Atypical neurofibromas are characterized by CDKN2A/B deletion in addition to NF1 loss, suggesting this is the next step in tumor progression." (PMID 37164978, 2023). "Homozygous loss of CDKN2A has also been suggested as an initiating event in the malignant transformation of neurofibromas in NF1 patients." (PMID 34816314, 2022). "Inactivating mutation in the cell cycle regulator locus CDKN2A subsequently promotes a neurofibroma’s progression into a pre-malignant state called atypical neurofibroma of uncertain potential (ANNUBP)." (PMID 34445326, 2021). "When broken down into histologic type, the most commonly affected tumor type was MPNST (60.7%, n = 262), in which CDKN2A loss has been shown previously to be a defining event for the malignant transformation of neurofibromas." (PMID 31528332, 2019). "Recurrent homozygous loss of the cyclin-dependent kinase inhibitor 2A (CDKN2A) locus was detected in majority of atypical neurofibromas." (PMID 23319880, 2012). "Chromosomal loss of CDKN2A was also one of few recurrent events in the benign neurofibromas." (PMID 37837931, 2023). "CDKN2A loss has also been observed to drive NF1 associated malignant transformation in neurofibromas, which may suggest an interaction between CDKN2A and NF1 in other tumor histologies as well that can potentially affect patient outcome." (PMID 36380219, 2022). "Interestingly, three other gross deletions at the CDKN2A locus, impacting on both p16 and p14, have been reported from melanoma-NST families, and a splice site mutation removing CDKN2A exon 2 was also found in a melanoma/neurofibroma family." (PMID 18612309, 2008). "CDKN2A/p16 inactivation is a well-recognized key event in the malignant transformation of neurofibromas in NF1." (PMID 38178234, 2024). "The homozygous deletion of 9p21.3 containing CDKN2A in atypical neurofibroma indicates that this is an early step in the progression of benign neurofibroma to atypia." (PMID 39409887, 2024). "The CDKN2A locus (9p21.3) was identified as the only target of recurrent homozygous deletions in both neurofibromas (n = 4, 14%, including the plexiform tumour) and MPNSTs (44%)." (PMID 37837931, 2023). "One example of such discordance is Case 105, diagnosed as schwannoma but showing a SNP array profile that was indicative of a neurofibroma (duplication in 5q, a homozygous deletion of CDKN2A, and LOH at NF1)." (PMID 35318454, 2022). "Of interest, studies showed that neurofibromas caused by NF1 mutation most often transition to malignant peripheral nerve sheath tumor through the co-mutation of PRC2 subunit genes and CDKN2A." (PMID 34090875, 2021).
neurofibroma (continued). "Loss of CDKN2A may occur prior to the transition from neurofibroma to MPNST, while H3K27me3, commonly present in neurofibromas, including ANNUBP, is frequently lost in MPNSTs, which may assist in their differentiation." (PMID 40308487, 2025). "To test this hypothesis, we analyzed a panel of patient-derived neurofibroma or MPNST cells with inactivating NF1, CDKN2A/B, or PRC2 mutations." (PMID 38216572, 2024). "Previous studies have suggested that loss of CDKN2A is exclusive to atypical neurofibromas and not present in benign plexiform neurofibromas." (PMID 37837931, 2023). "Interestingly, the polymorphism rs2151280 located in the lncRNA ANRIL (CDKN2B antisense RNA 1) was associated with the number of plexiform neurofibromas (PNFs) in NF1 patients, and 9p21.3 deletions, including the CDKN2A/B–ANRIL locus, are detected in PNFs." (PMID 31694342, 2019). "Similarly, CDKN2A loss is seen in the vast majority of atypical neurofibromas and in low-grade MPNSTs–but not in plexiform neurofibromas." (PMID 35053663, 2022). "Bidirectional sequencing revealed a heterozygous single nucleotide duplication in exon 2 of CDKN2A (NG_007485.1:g.28291dup) in DNA from a patient with five nerve sheath tumors (two were considered hybrid tumors with high schwann cell content but some neurofibroma features)." (PMID 35723634, 2022). "Based on a review of strong preclinical and clinical evidence, we propose the presence of CDKN2A/B biallelic inactivation as a sufficient molecular feature for the diagnosis of ANNUBP, even if the histopathology otherwise qualifies only for neurofibroma." (PMID 39500722, 2025). "We identified an out-of-frame fusion in an atypical neurofibroma (G3) involving CDKN2A and TMEM17, which represents a mechanism for CDKN2A inactivation." (PMID 37164978, 2023). "CDKN2A is a well-established human MPNST tumor suppressor, frequently lost in pre-malignant, atypical neurofibromas." (PMID 32353955, 2020). "The chromosome 9p21.3 region harbours a cluster of important growth regulatory genes (CDKN2A/ARF and CDKN2B) that are deleted or transcriptionally silenced in a wide range of tumours such as plexiform neurofibromas (PNF)." (PMID 23101500, 2012). "Furthermore, the silencing or homozygous deletion of CDKN2A, ARF, and CDKN2B has been detected in a subset of PNF, atypical neurofibromas, as well as MPNSTs, indicating that these genes have a role not only in the formation of PNFs, but probably also in MPNST development." (PMID 31694342, 2019). "A deletion at 9p21.3, which includes genes CDKN2A/2B, was identified in 15/16 (94%) ANF and in 16/23 (70%) high-grade MPNST but not in plexiform neurofibromas; supporting the hypothesis that ANF are premalignant tumors, with the CDKN2A/B deletion as the first step in the progression toward MPNST." (PMID 32014052, 2020).
esophageal squamous cell carcinoma (30 papers, 2008 to 2025). Esophageal squamous cell carcinoma (ESCC) is a type of esophageal carcinoma (EC) that can affect any part of the esophagus, but is usually located in the upper or middle third. "Previously, CDKN2A was shown to be associated with polymorphism of GSTs genes in esophageal squamous cell carcinoma." (PMID 35832557, 2022). "Immunohistochemical analysis has shown that the underexpressed RB protein in gastric adenocarcinoma and low expression of p16 (encoded by CDKN2A) in oral carcinoma, vertical growth phase melanoma, esophageal squamous cell carcinoma, and GBM significantly predict poor patient survival." (PMID 31815141, 2019). "The results of a whole-exome sequencing analysis revealed that CDKN2A was inactivated in 49–76% of esophageal squamous cell carcinoma and is considered as one of the key events in cancer development." (PMID 32556556, 2021). "And CDKN2A has been reported to promote the angiogenic phenotype and predict poor prognosis in esophageal squamous cell carcinoma." (PMID 34405225, 2021). "Promoter hypermethylation has been described as a main pathway for inactivation of CDKN2A for SCC of the esophagus, while deletion appears to happen early in the development of Barrett’s mucosa, a recognized precursor lesion for esophageal AC." (PMID 32256975, 2020). "The methylation of CDKN2A may be an early molecular event in the occurrence of esophageal squamous cell carcinoma." (PMID 38206516, 2024). "For example, Hypermethylated CDKN2A and CHFR were assessed as biomarkers for predicting radio resistance in esophageal squamous cell carcinoma." (PMID 37626750, 2023).